RNU6-1025P (RNA, U6 small nuclear 1025, pseudogene)
Gene: Small nuclear RNA gene on chromosome 11 (948,421 to 948,524, forward strand). Ensembl gene ENSG00000222561.
Homologues: Orthologues: chimpanzee U6 (98% identical), macaque U6 (89% identical), rat LOC120101181 (85% identical), mouse Gm24086 (75% identical), guinea pig U6 (64% identical). Paralogues in human: RNU6-1131P (88% identical), RNU6-115P (86% identical), RNU6-1331P (86% identical), RNU6-189P (86% identical), RNU6-1094P (85% identical), RNU6-1147P (85% identical), RNU6-15P (85% identical), RNU6-379P (85% identical), RNU6-384P (85% identical), RNU6-45P (85% identical), RNU6-500P (85% identical), RNU6-652P (85% identical), and 1285 more.